IL1R1 (interleukin 1 receptor type 1)
Diseases named in the same sentence as IL1R1 in open-access papers (continued):
Sharing a sentence is not in itself a finding about the gene and the disease.
infection (continued). "To examine whether inflammasome-deficient mice develop better B cell responses, we infected WT and Il1r1−/− mice with 0.1 × 106 YM iRBCs (five times lower dosage to keep WT mice survive longer) and collected serum at day 14 post infection." (PMID 30470758, 2018). "A group of Treg-signature genes (Areg, Arhpag20, Bub1b, Ccl12, Ccr5, Il1r1, Mki67 (Ki67) Ncf1, Nrp2, Tnfrsf9, Tcf19, Uhrf1, and Wnt3) were expressed at higher levels in IFNARfl/fl x Foxp3YFP-Cre mice than WT controls on day 5 Armstrong infection." (PMID 29672594, 2018). "Histological scores demonstrated that IL-1R1-/- mice exhibited less severe lung pathology than that of WT mice during the early infection stage, but significantly more severe lung pathology during the late infection stage." (PMID 28585438, 2017). "We document a sharp increase in the inflammatory response in terms of Ifng, Tnfa, Il6, Il1b, Il1r1, Cxcl9 and Cxcl10 expression already on day 6 post-infection in WT mice, and of Cd8a on day 7, which were essentially absent in ST2-/- mice on day 5 to 7 after PbA-infection." (PMID 28448579, 2017). "However, both disruption of the alveolar structure and formation of a hyaline membrane were seen in the lungs of dying IL-1R1-/- mice during late infection, with congestion and swelling of the lung interstitium." (PMID 28585438, 2017). "Rather, the eventual death of Il-1r1-/- mice may be due to failure of immune responses that are dependent on the presence of IL-1β in the early phase of infection but are effectively deployed only in the second week of infection." (PMID 25768794, 2015). "This could be because the loss of the homeostatic component of TNFR1, IL-1R1, and TLR signaling reduces the ability of an organism to resist infection, which, even in the weakened signaling environment of LUBAC deficiency, drives inflammatory signaling." (PMID 25443632, 2014). "Indeed, Il1r1−/− mice exhibit a significant decrease in neutrophil recruitment to the airway 24 hours post-infection, possibly contributing to their inability to efficiently clear the pathogen." (PMID 23762026, 2013). "Indeed, anti-inflammatory genes exhibited a considerable presence in the infection setting; the IL-10 family of genes important for wound healing and repair (IL1r2, IL1r1, IL-24, IL-19, IL-22) were elevated >2- to 60-fold, although IL-10 itself remained unchanged." (PMID 40586608, 2025). "Il1r1-/- mice exhibited more dramatic cortical bone changes, which may be due to differences in bone remodeling processes between WT and Il1r1-/- mice, the fact that Il1r1-/- mice harbor increased bacterial burdens over the duration of infection, or a combination of these factors." (PMID 30978245, 2019). "While mice deficient for IL-1R or inflammasome developed ECM after blood stage PbA-infection, MyD88-deficient mice were resistant to ECM after sporozoite PbA-infection, less so after blood-stage infection, pointing to a role of IL-1R1 pathway on the pre-hepatic stage of infection." (PMID 28448579, 2017). "A recent study reported that Ft-specific IgM produced by B1a B cells was significantly reduced in Il-1b/-, Il-1b-/-/Il-1a-/-, or Il-1r1-/- mice compared to C57BL/6J wildtype or Il-1a-/- mice and implicated as an explanation for susceptibility of IL-1β-deficient mice to pulmonary Ft LVS infection." (PMID 27926940, 2016). "Supporting the hypothesis that reduced titer of Ft-specific IgM is responsible for the susceptibility of Il-1r1-/- mice, passive transfer of serum obtained from Ft LVS infected C57BL/6J mice seven days p.i. protected naïve C57BL/6J mice from infection with lethal doses of Ft LVS." (PMID 25768794, 2015). "Mice double deficient for IL-1α plus IL-1β could not control the infection, similar to IL-1R1 deficient mice on day 35 post-infection, although bacterial burdens were not as high as those reached in TNF KO mice which succumbed at 4 weeks." (PMID 25400917, 2013).
infection (continued). "Confirming the different susceptibilities of Il-18-/- and Il-1r1-/- mice to melioidosis, the bacterial burdens observed in the lungs, spleens, livers, and BALF of infected Il-18-/- mice were dramatically higher than that of WT mice even at early time points (24 hours post infection)." (PMID 22241982, 2011). "The PPI observed that the hub genes with the largest number of associated nodes in the weighted network played a crucial role in the immune cell recruitment and activation after infection, such CXCR1, VNN2, BST1, CREM, IL1R1, and CD48." (PMID 39692191, 2025). "In terms of host-pathogen infection (e.g., mycobacterium tuberculosis), the H1N1 influenza virus IL-1R1 also plays an important role." (PMID 39211643, 2024). "We also found that KSHV de novo infection of primary endothelial cells increased the levels of IL1 signaling molecules, such as IL1β, IL1R1, IL1RAP, IL36α and IL36γ." (PMID 36457850, 2022). "While IL1R2, IL23R, IL1R1, IL-10, and CCL24 were highly upregulated upon infection of THP-1 macrophages, their expression was barely affected upon infection of primary macrophages." (PMID 34276658, 2021). "To validate IL-1β effects in vivo, we orally infected WT and IL-1R1-/- mice with CA and examined Foxp3+ cells in MOIL three days after infection and in vitro restimulation." (PMID 33240286, 2020). "In contrast, Il1r1-/- mice display significantly higher levels of GM-CSF and CXCL1 at day 5 post-infection when compared to WT mice, prior to the decrease in bacterial burdens that occurs between days 5 and 10 post-infection." (PMID 30978245, 2019). "Activation of TLR4, IL15R, IL1R1, and IL1A is important for antimicrobial activity, a key function for infection control." (PMID 29593724, 2018). "Among these, some became upregulated during the early stage of infection (day 4) CCL7, CXCL11, IL1R1 (cytokine receptor) and IL15RA, and others became upregulated during the late stage of infection (day 7): IL2RA, CSF2RB and others." (PMID 27595844, 2016). "Il1r1−/− mice indeed suffered more from the mild X31 IAV infection and displayed a tendency to higher viral titers in the lung, but did manage to clear infection with delayed kinetics, leading to a presumably higher viral exposure over time." (PMID 27579026, 2016). "Flow cytometry showed that in the liver-tissue samples from 48 and 72h post MHV-3 infection, the infiltration of CD45+Gr-1high neutrophils was substantially higher in the WT livers than that in the IL-1R1-/- littermates." (PMID 26367131, 2015). "Both macrophages and neutrophils express the IL-1 receptor (IL-1R1) on their surface and are the primary targets of the Y. pestis T3SS early during infection." (PMID 25781467, 2015). "The expression level of some proinflammatory molecules (e.g., CCR5, CXCR4, IL1A, IL1R1, IL8, and TNF) peaked on day 3 or 6 following infection." (PMID 25719526, 2015). "IL-1R1-/- mice manifested a significant reduction in hepatocellular damage and a decrease in serum ALT/AST levels during the infection." (PMID 26367131, 2015). "Interestingly, 100% of IL-1R1- or IL-18R1-deficient mice survived infection by rMA15 (data not shown) indicating that the genetic absence of either receptor did not recapitulate the lethal phenotype observed following infection of MyD88−/− mice." (PMID 19079579, 2008). "We identified 6 hub genes (IL1R1, CD163, TLR5, LY96, MMP9, and IRAK3) and 4 target miRNAs (miR-34a-5p, miR-103-3p, miR-107, and miR-124-3p) that affect the pathophysiological processes of T2DM and CS through ion transport, immune response, and infection." (PMID 40922361, 2025). "FCPLJ treatment downregulated several inflammatory cytokine genes in the liver, including CCL6/MRP-1, CCL8/MCP-2, CCL12/MCP-5, CCL17/TARC, IL1R1, IL1RN/IL1Ra, NAMPT/PBEF1, and PF4/CXCL4, indicating its potential role in mitigating inflammation during infection." (PMID 40007026, 2025).
infection (continued). "Analysis of the differentially expressed genes and pathways upon infection in Il1r1-/- and in control mice using Metascape37 uncovered an interesting transcriptional response in mice lacking IL-1R." (PMID 40097388, 2025). "To visualize the infection in-vivo, we performed histological staining for fungi, using Modified Grocott Methanamine Silver (GMS) staining, in kidney and brain sections from day 2 infected Il1r1-/- mice and Il1r1+/- controls." (PMID 40097388, 2025). "In contrast, the addition of 1 uM and 10 uM of C-PTIO was sufficient to increase the susceptibility of Ifnar1-/- and Il1r1-/- BMDMs, respectively, while adding any amount of C-PTIO did not impact the course of infection in DKO BMDMs." (PMID 38603763, 2024). "After 3 days of infection, histopathologic examination of lung tissues from infected animals revealed that, unlike wild-type mice, IL-1R1-/- mice were unable to contain hyphae within the agar beads." (PMID 34322116, 2021). "Along these lines, it has been proposed that IL-1R1 on nonimmune cells was required for the ability of infected alveolar macrophages to leave the airway to establish infection in the interstitial lung space." (PMID 33952660, 2021). "IL-1R1−/− mice fail to clear infection with lymphocytic choriomeningitis virus (LCMV) and LCMV-specific CD8+ T cells from IL-1R1-deficient mice do not synthesize granzymes and lack potent cytolytic activities." (PMID 33584721, 2020). "Il1r1−/− mice had systematically higher viral loads during the entire course of infection and did not clear the infection completely at 8 dpi as an estimated remaining titer of 100,000 viral particles is detected at this time point." (PMID 27579026, 2016). "Bacterial burden remains elevated in the absence of IL-1R signaling, with the Il1r1−/− mice still exhibiting a log-increase in bacterial load at 120 hours post-infection." (PMID 23762026, 2013). "The lung lesions observed in the absence of both IL-1α and IL-1β were similar to those seen in mice deficient for IL-1R1 or TNF, although confluent necrosis was more pronounced in the absence of TNF 4 weeks post-infection." (PMID 25400917, 2013). "CFU assays were performed at 72 hours after infection and demonstrated that siRNA-mediated knockdown of DEFB4 expression permitted levels of bacterial proliferation similar to what was observed in knockdown of IL1R1." (PMID 23762029, 2013). "Also, massive NETs and elevated neutrophil numbers were observed in the brains and kidneys of Il1r1-/- mice 2–3 days after infection, indicating no general defect in neutrophil recruitment and function." (PMID 40097388, 2025). "As both infections induced high levels of cell death in the Il1r1-/- BMDMs, but not in the DKO BMDMs, these responses could be a general response to Mtb infection that is mediated by type I IFNs." (PMID 38603763, 2024). "While these increased frequency of cell death in Il1r1-/- BMDMs coincided with their inability to control wt Mtb infection, the same does not appear to be the case during rpoB Mtb mutant infection, suggesting a role for other host cellular processes to mediate protection against rpoB-H445Y Mtb." (PMID 38603763, 2024). "No further delay in migration was observed in the Mtb-LT1 infection with α-IL-1R1 treatment." (PMID 35173157, 2022). "Importantly, these differences were restricted to the site of infection, as there were no deficits in any immune cell compartments in the spleens of IL-1R1 KO mice." (PMID 32703941, 2020). "The immune deficits in IL-1R1 KO mice are also specific to chronic infection as IL-1R1 KO mice analyzed earlier during infection (12 dpi) displayed no deficit in their monocyte/macrophage or T cell populations compared to WT in the peritoneal cavity or the spleen." (PMID 32703941, 2020).
infection (continued). "In light of data suggesting a critical role of IL-1 receptor signaling in controlling infection with West Nile virus (WNV), an emerging flavivirus like ZIKV, we additionally wanted to assess ZIKV disease manifestation and cellular infiltration in the brains of IL-1R1 KO mice." (PMID 32973802, 2020). "Circulating concentrations of IL-1 never reach high levels apart from in severe infection but circulating immune cells may deliver IL-1 to the cerebrovasculature, where IL-1R1 expression in the brain is highest." (PMID 30453020, 2019). "At this time point of infection, around 50% of CD44hiCD4+ T cells express the master gene of Th1 cells, T-bet, and the majority of T-bet+CD44hiCD4+ T cells expresses IL-18R1 but not IL-1R1." (PMID 28895840, 2017). "Furthermore, Il1r1−/− BMDCs did not demonstrate any defect in IL-1β secretion after 24 h of infection with Mtb, since in wild-type and knock-out BMDCs about 4ng/ml of IL-1β were secreted." (PMID 22911706, 2012). "Previously we have shown that the IL-1R1 deficient mice are more susceptible to systemic dissemination in our OPC model using the GDH-2346 strain including higher oral fungal burdens, although differences were more notable at 7 days of infection rather than the 3 days shown here." (PMID 33007818, 2020). "There was no change in the expression of the receptors IL1-R1 and CXCR2 within the site of infection or on the circulating leukocytes." (PMID 39509414, 2024). "Functionally, loss of IL-1rn in vivo biases HSC differentiation into the myeloid lineage and induces excess myeloid lineage expansion reminiscent of early hematological disease, through IL-1r1 and IL-1β overactivation in HSC but not IL-1α, in the absence of injury or infection." (PMID 36596811, 2023). "IL-1R1 was observed to be scattered throughout the intestine, and was particularly prodominant on IEC cells, although expression levels did not alter following infection." (PMID 23935505, 2013).
cancer (95 papers, 2002 to 2026). A tumor composed of atypical neoplastic, often pleomorphic cells that invade other tissues. "Accordingly, CRC patients who present with IL1R1-expressing cancer-associated-fibroblasts (CAFs), also display elevated levels of immune exhaustion markers, as well as an increased Th17 score and an overall worse survival." (PMID 37460545, 2023). "Genes Fam65b and Il1r1 are known to play a role in cancer, and liver-, or inflammation-associated diseases." (PMID 25918251, 2015). "Thus, a target of Anakinra (IL1R1) was associated with the module of extracellular matrix biology distinctly in the different cancer types." (PMID 27824868, 2016). "Cancer-associated fibroblasts (CAFs) contribute to the malignant aggressiveness through secreted factors like IL1β, which may drive pro-tumorigenic inflammatory phenotypes mainly acting via the cognate receptor named IL1R1." (PMID 27072893, 2016). "IL-1β-IL-1R1 signaling is required for IEC SIRT3 deficiency-induced TH1 and CTL differentiation in cancer." (PMID 41487042, 2026). "A key mechanism by which IL-1R1 drives cancer progression is by orchestrating an immunosuppressive TME." (PMID 41415279, 2025). "This occurs through IL-1β/IL-1R1 signaling, which is activated under hypoxic conditions and drives aggressive behavior in triple-negative BC (TNBC) and cancer-associated fibroblasts." (PMID 41150737, 2025). "As such, anakinra, an IL-1 receptor (IL1R1) antagonist, is being or has been investigated in combination therapies for many of these cancers to enhance chemosensitivity." (PMID 40299479, 2025). "By releasing IL‐1β, OSCC cells enhance tube formation capacity of LECs via IL‐1β directly binding to IL‐1R‐1 in LECs, suggesting the potentials of IL‐1β/IL‐1R‐1 axis in promoting cancer‐related lymphangiogenesis and LN metastasis of OSCC." (PMID 40135589, 2025). "CRISPR-Cas9 mediated knockout of IL6ST and IL1R1 in cancer cells suppressed the growth advantage of the neutrophil-CTC clusters without effect on their frequency." (PMID 37006265, 2023). "Expression of adhesion molecule ICAM1 also predicts poor prognosis for several cancer types, closely mimicking the effects observed for the IL1R1 and IL6R genes." (PMID 37006265, 2023). "Some BIIGs were downregulated in various cancers, especially Il1r1, Srgn, Emp1, Ptx3, Socs3, and Cebpd, which were downregulated in at least seven cancer types." (PMID 36605216, 2022). "We demonstrated that the “highly infiltrated” CRCs have a defect in Th1 cytotoxic signature, an excess of inhibitory checkpoint molecule PD-L1 and are likely rich in IL1R1+ Tregs, a subset of cancer-specific and high immunosuppressive Tregs." (PMID 36497365, 2022). "To confirm the importance of IL1 signaling in iCAF formation, we treated cancer cell-PSC cocultures with an IL1 receptor (IL1R1)-neutralizing antibody, which resulted in the impaired acquisition of the iCAF phenotype under hypoxia." (PMID 36109493, 2022). "The cancer colonocytes responded to the presence of the mixture of fecal bacteria and hPA120 (V BM + hPA120 and O BM + hPA120 samples) by an increase of IL1R1 and a decrease of MYD88 expression compared to CTRL and/or hPA120 controls." (PMID 36296918, 2022). "Recent studies have reported that the IL-1β/IL-1R1 signaling pathway promotes cancer proliferation, invasion and metastasis in several cancers." (PMID 32206125, 2020). "Inhibition of IL-1β/IL-1R1 signaling by Anakinra treatment significantly inhibited cancer proliferation and metastasis 27-29." (PMID 32206125, 2020). "In that setting, interleukin 1 beta IL1B released by macrophages signals via the interleukin 1 receptor type 1 (IL1R1) on the cancer cells to maintain high expression of ZEB1." (PMID 31623163, 2019). "Thereby, ligand-activation of GPER generates a feedforward loop coupling IL1β induction by CAFs to IL1R1 expression by cancer cells, promoting the up-regulation of IL1β/IL1R1 target genes such as PTGES, COX2, RAGE and ABCG2." (PMID 27072893, 2016).